KRAS (KRas proto-oncogene, GTPase)
Diseases named in the same sentence as KRAS in open-access papers (continued):
Sharing a sentence is not in itself a finding about the gene and the disease.
adenomyosis (continued). "To investigate whether the reduced PR protein in KRAS-mutated adenomyosis samples was due to an effect of mutant KRAS on PR mRNA expression, we applied qPCR analysis to our immortalized endometrial cells overexpressing KRAS-Mut, KRAS-WT, PIK3CA-WT, or PIK3CA-Mut (please see the Source Data file)." (PMID 31857578, 2019). "However, the frequency and VAF of such mutated clones were significantly elevated in adenomyosis samples, suggesting that additional alterations in KRAS-mutated clones in the NE might occur very early during the molecular pathogenesis of adenomyosis." (PMID 31857578, 2019). "Furthermore, this review underscores the significance of continuous STAT3 activation in promoting adenomyosis and the intriguing hypothesis that KRAS mutations could potentially serve as biomarkers for treatment efficacy, opening doors to genetically guided therapies." (PMID 37834773, 2023). "In contrast, there was a marked increase in the methylation level of the PR-A/B promoters in KRAS-Mut adenomyosis." (PMID 31857578, 2019). "We also detected these mutations in NE adjacent to adenomyotic lesions, prompting us to investigate the relevance of KRAS- and PIK3CA-mutated clones to the molecular pathogenesis of adenomyosis." (PMID 31857578, 2019). "As in endometriosis, lesions of adenomyosis and their surrounding normal tissues have KRAS mutations, even though they are not cancerous." (PMID 36291839, 2022). "Furthermore, we provide functional evidence for the role of mutant KRAS in mediating the efficacy of DNG as an adenomyosis therapy." (PMID 31857578, 2019). "Our analyses revealed intriguing clinical differences between cases of adenomyosis with KRAS mutations vs. those without." (PMID 31857578, 2019). "However, adenomyosis and uterine endometrium of subject 6 shared only one mutation (KRAS p.G12V) and none other." (PMID 40679511, 2025). "The pathways enriched among the upregulated genes in the HSD17B1TG uterus included inflammation, late estrogen response, KRAS signaling and regulation of cell adhesion, further supporting the hypothesis that these pathways are involved in the development of adenomyosis." (PMID 35563206, 2022). "Recurrent mutations, such as KRAS, PIK3CA (phosphatidylinositol-4,5-bisphosphate 3-kinase), PPP2R1A (Protein Phosphatase 2 Scaffold Subunit Alpha), and ARID1A (AT-Rich Interaction Domain 1A), are observed in endometriosis and adenomyosis, which suggests similar disease development." (PMID 35206475, 2022). "Taken together, these data support our hypothesis #1 (KRAS-mutated adenomyotic clones are less sensitive to DNG treatment) rather than hypothesis #2 (DNG drives KRAS mutations in adenomyosis patients)." (PMID 31857578, 2019). "To investigate whether increased DNA methylation was involved in downregulating PR in KRAS-Mut adenomyosis, we performed bisulfite sequencing of DNA from the enriched epithelial component of adenomyotic lesions from PR-expressing KRAS-WT samples (n = 20) and from all 13 PR-negative KRAS-Mut samples." (PMID 31857578, 2019). "In our cohort of adenomyosis patients, pretreatment with LNG-IUS, an intrauterine device producing local progestin, showed no outcome correlation with the presence of KRAS mutations." (PMID 31857578, 2019). "In PR-expressing KRAS-WT adenomyosis, no significant DNA methylation of CpG islands in the PR-A/B promoters was detected." (PMID 31857578, 2019).
adenomyosis (continued). "The mutation frequencies per subject, regardless of sampling depths, were as follows: in adenomyosis, KRAS: 33.3%, PIK3CA: 14.3%, and ARID1A: 14.3%, and in uterine endometrium, KRAS: 66.7%, PIK3CA: 57.1%, ARHGAP35: 52.4%, PPP2R1A: 33.3%, PIK3R1: 28.6%, and FGFR2: 19.0%." (PMID 40679511, 2025). "Obviously, further investigations are required to establish the validity of this approach, but investigation of the KRAS and PIK3CA mutation status of non-diseased uterine tissue of adenomyosis patients might greatly aid in surgical decision-making and therapeutic management." (PMID 31857578, 2019).
head and neck cancer (25 papers, 2009 to 2026). A primary or metastatic malignant neoplasm affecting the head and neck. "In colorectal, and head and neck cancers, KRAS mutation, EGFR-S492R mutation, and increased ErBb signaling are responsible for resistance against Cetuximab." (PMID 26904540, 2016). "The work in this study is a hypothesis-generating evaluation of the KRAS-variant as a potential biomarker to help predict outcomes and toxicity in patients with head and neck cancer treated with radiation and cetuximab." (PMID 41790036, 2026). "Activating mutations in one of the three RAS genes (HRAS, KRAS, and NRAS) are observed in 5–10% of patients with head and neck cancer, and HRAS mutations in particular are detected in > 50% of patients with head and neck cancer." (PMID 29374236, 2018). "In patients with gastric, breast, and head and neck cancers with no KRAS oncogenic mutations, KRAS overexpression is associated with poor prognosis." (PMID 35546148, 2022). "The v-Ki-ras2 Kirsten rat sarcoma viral oncogene homolog (KRAS)-LCS6 (G>T) polymorphism is located in the KRAS2 gene (region 12p12.1, 6 exons; exon 5 has an alternative splicing site and results in the B isoform, KRASB) and appears to reduce the lifespan of head and neck cancer patients." (PMID 24932237, 2014). "There are other potential biomarkers that have been studied in head and neck cancer, including EGFR, KRAS, PIK3CA, and p16INK4a protein." (PMID 36980171, 2023).
intraductal papillary mucinous neoplasms (25 papers, 2014 to 2025). "The high sensitivity of KRAS/GNAS mutations in conjunction with specificity regarding IPMNs (intraductal papillary mucinous neoplasms) and mucinous PCs (pancreatic cysts) respectively is noticed during NGS strategy regarding PCF contrasting Sanger sequencing." (PMID 39605899, 2024). "In mouse models, disrupted ARID1A promoted the carcinogenesis from KRAS-mutated premalignant intraductal papillary mucinous neoplasms (IPMN) to PDAC44." (PMID 38310130, 2024). "This pooled analysis using data from 1253, 835, and 143 pancreatic IPMN patients revealed that overall KRAS, GNAS, and RNF43 mutations were detected in 61, 56, and 23 %, respectively." (PMID 27512631, 2016). "The purpose of this report is to introduce seven new cases and to compare their clinicopathologic features and KRAS mutations to gastric-type intraductal papillary mucinous neoplasms (IPMNs) and intraductal tubulopapillary neoplasms (ITPNs)." (PMID 25245835, 2014). "In addition, we also observed independent intraductal papillary mucinous neoplasms with KRAS G12V and GNAS R201H mutations." (PMID 32582528, 2020). "KRAS activation is observed in precursor lesions such as pancreatic intraepithelial neoplasia (PanIN) and intraductal papillary mucinous neoplasm (IPMN), identifying it as a major genetic driver." (PMID 40762406, 2025). "KRAS mutations are also detected in early precursor lesions of PDAC, including low-grade pancreatic intraepithelial neoplasia (PanINs) and intraductal papillary mucinous neoplasms (IPMNs), underscoring their role in the initiation of neoplastic transformation." (PMID 41228342, 2025). "At 8, 12, and 16 months of age, KRAS mice on standard isocaloric control or ω6-enriched diets had 100% penetrance of cystic papillary neoplasms (CPNs; resembling IPMNs or Intraductal Papillary Mucinous Neoplasms)." (PMID 30213082, 2018). "The prevalence and clinical significances of KRAS, GNAS, and RNF43 mutations in patients with pancreatic intraductal papillary mucinous neoplasm (IPMN) remain elusive." (PMID 27512631, 2016). "KRAS mutation occurs early in PDAC cancerogenesis, and can also be found in preneoplastic pancreatic lesions, as pancreatic intraepithelial neoplasia (PanIN) and intraductal papillary mucinous neoplasm (IPMN)." (PMID 34064352, 2021). "PDAC can arise from mucinous precursor lesions, including the most common, pancreatic intra-epithelial neoplasia (PanIN), as well as intraductal papillary mucinous neoplasms (IPMN) and Mucinous Cystic Neoplasms (MCN), with activating KRAS mutations frequently found in these early neoplastic stages." (PMID 30014851, 2018). "This study demonstrates that KRAS and GNAS mutations are more prevalent in patients with resected intraductal papillary mucinous neoplasms (IPMN) compared to those under clinical surveillance." (PMID 39219164, 2025). "Concurrent activation of the KRAS and GNAS mediated signaling pathways appears to be shared with pancreatic intraductal papillary mucinous neoplasm." (PMID 24944587, 2014). "Its expression along with KRAS is common in intraductal papillary mucinous neoplasms (IPMN), but there is no clear correlation with its malignant transformation." (PMID 34205412, 2021).
rectal adenocarcinoma (25 papers, 2017 to 2026). "In our study (case 4BC-19), real-time PCR of a rectal adenocarcinoma patient showed the expression of two different clonal mutations (G12V and G12C) at the same codon position (codon 12) of KRAS gene." (PMID 36994199, 2023). "We determined the KRAS mutational profile in all rectal adenocarcinoma samples that were included which allowed a comparison with CAIX expression data." (PMID 36768903, 2023). "On the other hand, among KRAS mutations in colon and rectal adenocarcinoma, G13 mutations are observed in relatively high frequencies (20 and 21%, respectively)." (PMID 35045886, 2022). "In this cohort, we were able to evaluate the relationship of CAIX expression with the KRAS mutational status which proved to be correlated, as KRAS mutant rectal adenocarcinomas presented initially and following neoadjuvant therapy with significantly higher CAIX scores and CAIXhigh phenotype." (PMID 36768903, 2023). "We profiled mRNA in 76 locally advanced rectal adenocarcinomas from patients that were enrolled in a prospective clinical trial and investigated differences in gene expression between KRAS mutant (KRAS‐mt) and KRAS‐wild‐type (KRAS‐wt) patients." (PMID 33817986, 2021). "The patient was a 53-year-old male with rectal adenocarcinoma (mismatch repair proficient, KRAS and BRAF wild-type) with pelvic and lung metastases." (PMID 32377194, 2020). "Overall mucinous rectal cancers are more likely to be MSI-H and to have KRAS, BRAF, and PIK3CA mutations when compared to rectal adenocarcinoma NOS." (PMID 32984045, 2020). "In the PanCanAtlas, KRAS mutations were widespread in PAAD (72%), COAD (45%), rectum adenocarcinoma (READ, 42%), and LUAD (31%), while NRAS mutations were common in SKCM (31%)." (PMID 29617658, 2018). "Next, we analyzed the cell line RCM1, a rectal adenocarcinoma cell line with KRAS-G12V mutation without HLA-A*11:01, to determine whether any oncogenic KRAS-carrying neoantigens would be identified from different HLA allotypes." (PMID 35982173, 2022). "A 55-year-old woman was diagnosed as adenocarcinoma of the rectum and the primary tumor was detected to be Kirsten-RAS (KRAS) wild type." (PMID 31852167, 2019).
colon adenoma (24 papers, 2011 to 2025). An adenoma that arises from the colon. "One recent report of a proximal gastric adenocarcinoma in a FAP patient described a molecular pathway similar to the colonic adenoma-carcinoma sequence with somatic KRAS and PIK3CA mutations." (PMID 39776297, 2025). "Recent research has shown that TBX19 gene, which is increased in colon adenomas, was identified as one of the genes triggered by KRAS mutations." (PMID 36999050, 2023). "KRAS G12D and G12V mutations are more abundant in colonic adenomas, as compared to normal colonic mucosa, suggesting these mutations confer a selective advantage early in carcinogenesis." (PMID 28755461, 2017). "Of note, APC and KRAS, genes that are mutated early in colon adenoma–carcinoma progression, were dominantly mutated in MSC-2, which implies that familial adenomatous polyposis (FAP) may be one of the main causes of MSC-2." (PMID 33959500, 2021). "KRAS mutations are frequently found after APC inactivation in large colonic adenomas." (PMID 33135632, 2020). "However, it is likewise reasonable that genetic heterogeneity defines colon adenomas and that KRAS and BRAF mutations are subclonal." (PMID 30166531, 2018). "Furthermore, similar to what is seen in colonic adenomas, KRAS mutations occur in benign ampullary adenomas, suggesting activating mutations of KRAS are relatively early events in the progression toward cancer and the mutation does not appear to affect prognosis." (PMID 22762308, 2012). "In summary, we report widespread genetic heterogeneity within colon adenomas and show that this heterogeneity affects genes and pathways functionally associated with the development of CRC, such as APC, KRAS and the MMR." (PMID 30166531, 2018). "Significant differences in MF were observed among sample types (Kruskal‐Wallis test, P = 0.0013), with colonic adenomas having significantly greater KRAS G12D mutant levels than normal colonic mucosa." (PMID 28755461, 2017). "The current model suggests that oncogenic KRAS promotes the malignant transformation of colon adenoma to carcinoma through further hyperactivation of WNT signaling." (PMID 26744320, 2016). "We also aimed to determine whether KRAS, BRAF mutations, and/or MLH1 hypermethylation is associated with Fn infection in colon adenomas." (PMID 37772997, 2023). "While changes in cfDNA or mutations were not detectable, NGS analysis unmasked extensive genetic heterogeneity of colonic adenomas, affecting known drivers such as APC, KRAS and MMR genes." (PMID 30166531, 2018).
gastric tumor (22 papers, 2009 to 2024). "A hairpin-DNA that recognizes KRAS mutations and conjugates with Cy3-AuNPs can be highly effective in identifying gastric tumors." (PMID 36615558, 2023). "Codon 12 and codon 59 KRAS mutations are most commonly found in the large intestine tumors and to a lesser extent in lung, hematopoietic and stomach tumors." (PMID 31009485, 2019). "The aim of the present study was to evaluate EGFR and HER-2 immunohistochemical expression and KRAS mutational status in a series of canine gastric tumours." (PMID 24454858, 2014). "KRAS mutant gastric tumor samples (TCGA-STAD) also showed significantly higher expression of CCNA2 (p = 4.76 × 10−4 by Wilcoxon test) than wild-type gastric tumors." (PMID 32486290, 2020). "Within the KRAS amplified gastric tumors 14/27 (51.9%) showed a heterogeneous distribution with also KRAS non-amplified tumor parts." (PMID 32571252, 2020). "This method can also be applied to gastric tumors using KRAS as the target." (PMID 36615558, 2023). "In addition, the gastric tumor with TPM3::NTRK1 (T8;N10) rearrangement also simultaneously carried the p.G12C mutation in the KRAS oncogene." (PMID 37686416, 2023). "Previous studies have shown that KRAS plays critical roles in gastric tumor development." (PMID 33888645, 2021). "However, neither cells bearing KRAS amplification (6% of gastric tumours) nor KRAS mutations (7%) can be killed with a single KRAS-targeted drug." (PMID 38261067, 2024). "Despite the enhanced proliferation of dysplastic glands, Hp+/KRAS+ mice did not develop gastric tumors within 12 wk." (PMID 33310760, 2021). "However, Hp+KRAS+ mice did not develop gastric tumors within a 3- to 4-month experimental time frame." (PMID 37674528, 2023). "No EBV or MSI-related gastric tumors harboured KRAS amplification." (PMID 32571252, 2020). "In six cases (out of 14 KRAS amplified tumors with lymph node metastases) we could detect KRAS amplification in regional lymph node metastases but not in the primary available parts of the gastric tumor on TMA." (PMID 32571252, 2020).